STIMATE (STIM activating enhancer)
Description:
Acts as a regulator of store-operated Ca(2+) entry (SOCE) at junctional sites that connect the endoplasmic reticulum (ER) and plasma membrane (PM), called ER-plasma membrane (ER-PM) junction or cortical ER. SOCE is a Ca(2+) influx following depletion of intracellular Ca(2+) stores. Acts by interacting with STIM1, promoting STIM1 conformational switch. Involved in STIM1 relocalization to ER-PM junctions. Contributes to the maintenance and reorganization of store-dependent ER-PM junctions.
Synonyms: TMEM110; MGC52022
Tractability: Antibody: UniProt predicts a signal peptide or a membrane-spanning region. PROTAC: ubiquitination databases record sites on it.
Gene: Protein-coding gene on chromosome 3 (52,836,219 to 52,897,578, reverse strand). Ensembl gene ENSG00000213533.
Subcellular location: Endoplasmic reticulum membrane
Subcellular location (Human Protein Atlas): Cytosol
Gene Ontology:
Molecular function: calcium channel regulator activity; protein binding
Biological process: activation of store-operated calcium channel activity; store-operated calcium entry
Cellular component: cortical endoplasmic reticulum; endoplasmic reticulum membrane; endoplasmic reticulum-plasma membrane contact site; membrane
Genetic constraint (gnomAD): Loss-of-function variants: 15 observed, 35.25 expected, observed/expected ratio (o/e) 0.43, 90% interval 0.28 to 0.65. The upper end of that interval is the gene's LOEUF score, 0.65, which puts it in group 2 of 6, group 1 being the genes least tolerant of losing a copy. Missense variants: 305 observed, 378.86 expected, observed/expected ratio (o/e) 0.81, 90% interval 0.73 to 0.88. Synonymous variants: 163 observed, 154.35 expected, observed/expected ratio (o/e) 1.06, 90% interval 0.93 to 1.2.
Homologues: Orthologues: chimpanzee STIMATE (99% identical), macaque STIMATE (99% identical), dog STIMATE (99% identical), pig STIMATE (98% identical), guinea pig STIMATE (97% identical), mouse Stimate (96% identical), rat Stimate (88% identical), zebrafish stimate (74% identical), tropical clawed frog stimate (73% identical), rabbit STIMATE (68% identical). Paralogues in human: MUSTN1 (4% identical).
Diseases named in the same sentence as STIMATE in open-access papers:
STIMATE is named in the same sentence as 11 diseases in open-access papers, as found by Europe PMC text mining. Sharing a sentence is not in itself a finding about the gene and the disease. The quoted sentences say what the papers report.
fatty liver disease (1 paper, 2023). A reversible condition wherein large vacuoles of triglyceride fat accumulate in liver cells via the process of steatosis. "STIMATE encodes a store-operated Ca2+ junction regulator that indirectly interacts with the STIM1 calcium channel regulatory protein, whose dysfunction is related to fatty liver disease." (PMID 37859957, 2023).
cancer (1 paper, 2022). A tumor composed of atypical neoplastic, often pleomorphic cells that invade other tissues. "There are plenty of regulatory proteins, including CRACR2A, SEPTIN4, STIMATE, GOLLI, SARAF, ORMDL3 and so on, that contribute to alter SOCE activity in cancer, immune diseases and inflammation disorders." (PMID 36128650, 2022).
STIMATE also shares sentences with these, for which no sentence is quoted: schizophrenia (3 papers); bipolar disorder (1); depression (1); diabetes (1); immune diseases (1); lung carcinoma (1); mood disorder (1); Obesity (1); Sepsis (1).